FMNL1 (formin like 1)
Diseases named in the same sentence as FMNL1 in open-access papers (continued):
Sharing a sentence is not in itself a finding about the gene and the disease.
pancreatic cancer (1 paper, 2025). "In 2011, in the study where FMNL1 was shown for the first time in epithelial cancers, its expressions were also found in Jurkat, HeLa, and pancreatic cancer cell lines." (PMID 40864802, 2025).
periodontitis (1 paper, 2022). An acute or chronic inflammatory process that affects the tissues that surround and support the teeth. "The potential role of FMNL1 in enhancing macrophage activity might be involved in the mechanism of periodontitis inducing PD progression." (PMID 36545026, 2022). "Based on these studies, it may be suggested that the crosstalk gene FMNL1 is a common link between periodontitis and PD via macrophage activation." (PMID 36545026, 2022). "However, there is no published research investigating the deregulation and function of FMNL1 in linking periodontitis and PD to date." (PMID 36545026, 2022). "In periodontitis, MANSC1 was negatively correlated and the other four hub crosstalk genes (FMNL1, PLAUR, RNASE6, and TCIRG1) were positively correlated with five hub IRRGs, namely, AQP9, C5AR1, CD14, CSF3R, and PLAUR." (PMID 36545026, 2022). "Five genes (i.e., FMNL1, MANSC1, PLAUR, RNASE6, and TCIRG1) were identified as crosstalk biomarkers linking PD and periodontitis." (PMID 36545026, 2022). "The main findings of the current study identified five hub crosstalk genes (i.e., FMNL1, MANSC1, PLAUR, RNASE6, and TCIRG1) to be the linking mechanisms between periodontitis and PD." (PMID 36545026, 2022).
prostate carcinoma (1 paper, 2025). A carcinoma that arises from epithelial cells of the prostate gland. "In this study on prostate cancer, we investigated FMNL1 and PAK1 in prostate cancer patients." (PMID 40864802, 2025). "Given the significant roles of FMNL1 and PAK1—two molecules involved in actin polymerization and cell motility—we hypothesized that their expression levels would be elevated in prostate cancer patients, particularly in advanced stages." (PMID 40864802, 2025).
type 1 diabetes (1 paper, 2020). "FMNL1-deficient T cells are impaired in trafficking to the pancreatic islets and inducing type 1 diabetes." (PMID 32510333, 2020).
cancer (17 papers, 2008 to 2025). A tumor composed of atypical neoplastic, often pleomorphic cells that invade other tissues. "The FMNL1 expression was substantially linked with the majority of TIICs in pan-cancer, with the exception of PCPG, according to the results of the computation of TIICs in the TME using the ssGSEA method." (PMID 37859818, 2023). "FMNL1 expression was positively correlated with the T-cell inflamed score, an alternative indicator to evaluate the clinical response to immunotherapy, and the activities associated with most steps of cancer immunity cycle were significantly upregulated in the high FMNL1 group." (PMID 37859818, 2023). "Additionally, the associations between FMNL1 and immune checkpoint expressions in various cancer types were examined, and the results were equally encouraging." (PMID 37859818, 2023). "These protrusions are dependent on the actin-polymerizing protein FMNL1, and Rab25 coordinates the activity of RhoA with the arrival of FMNL1 and integrin β1 cargos to form protrusions that promote invasive migration of cancer cells in the 3D matrix." (PMID 40614209, 2025). "As the first study to report FMNL1 protein expression in cancer types other than hematological cancers, the study conducted in 2014, in which 28 different cancer tissues were examined, stands out." (PMID 40864802, 2025). "Collectively, these findings suggest that bulk FMNL1 mRNA expression is a pan-cancer classifier that identifies immuno-hot tumors and forecasts immunotherapy response." (PMID 37859818, 2023). "Given the oncogenic role of FMNL1 in human cancers 8, 9, the contradictory prognostic phenotype was puzzling." (PMID 37859818, 2023). "As a matter of course, patients with high FMNL1 expression should exhibit better responses to immunotherapy due to the tight immunological correlations of FMNL1 in pan-cancer." (PMID 37859818, 2023). "FMNL1 was also found in tumor cells, indicating that it functions as a critical oncogene in a variety of cancers." (PMID 36124068, 2022). "Comparing the expression of FMNL1 in the normal tissues and cancer tissues, the stages 1, 2, and 3 have great difference to the normal tissues." (PMID 36124068, 2022). "FMNL1 expression was shown to be upregulated in a variety of cancers, and this upregulation aided cell invasiveness." (PMID 36124068, 2022). "In vitro experiments presented the functional effects of FMNL1 knockdown on the inhibition of proliferation, migration and invasion in cancer cell lines." (PMID 34659547, 2021). "Representative microphotograph showed that the positive expression of FMNL1 was localized to the membrane and cytoplasm of cancer cells." (PMID 34659547, 2021). "Filamin A (FLNA), plastin-2 (LCP1), coronin-1A (CORO1A), and formin-like-1 (FMNL1) also affect cytoskeletal dynamics by modulating actin filaments which eventually prompt cancer mobility and invasion." (PMID 32326232, 2020). "Whether bulk FMNL1 mRNA expression was correlated with the immuno-hot TME in pan-cancer was next assessed." (PMID 37859818, 2023). "As a result, we hypothesized that the balance of FMNL1 expression in tumor and immune cells resulted in different prognostic phenotypes in various cancers." (PMID 36124068, 2022). "It was found that eight proteins (ADD2, DEF6, DOK3, ENO2, FMNL1, MICALL2, PARVG, and PSTPIP1) in KIRC cancer were more highly expressed in tumor tissues (100%), compared with normal tissues." (PMID 36428765, 2022). "This can lead to an overestimation of the cancer cell-specific mRNA expression, while in our approach, we only analyzed cancer cell-specific FHOD1 and FMNL1 staining and disregarded the strongly stained immune cells from our scoring results." (PMID 34115237, 2021). "RNA analyses are typically performed from tissue bulk containing not only cancer cells but also mesenchymal cells, including FHOD1 and FMNL1 expressing immune cells." (PMID 34115237, 2021). "However, the role of formin-like 1 (FMNL1) in cancer remains unclear." (PMID 31861134, 2019).
cancer (continued). "Due to the specific expression pattern of FMNL1, its obvious correlation with immune TME could be observed in routine analysis based on bulk RNA-seq data, and its function act as a cancer immunologically correlated gene may be irrelevantly speculate." (PMID 37859818, 2023). "In cancer cells, FHOD1 and FMNL1 showed different intensities of cytoplasmic expression." (PMID 34115237, 2021). "As a result, FMNL1, FMNL2, and FMNL3 are correlated with poor prognosis in several cancers." (PMID 31861134, 2019). "Hovever, the expression pattern of FMNL1 in cancer has not been well explored." (PMID 37859818, 2023). "Although FMNL1 was tightly correlated with immune infiltration in HCC, and even in pan-cancer, it was a novel biomarker for immune cells, but might not be a critical regulator in tumor cells to mediate tumor immunity due to the distinctive expression pattern of FMNL1." (PMID 37859818, 2023).
tumor (15 papers, 2018 to 2025). "It has been stated that high FMNL1 expression is associated with high tumor grade, tumor metastasis, and poor prognosis by increasing cell migration and invasion." (PMID 40864802, 2025). "FHOD1 and FMNL1 proteins are expressed in the tumor cells of intestinal GC and significantly associate with clinical parameters without direct prognostic significance." (PMID 34115237, 2021). "Intermediate FMNL1 expression in the peripheral tumor part associated significantly with higher tumor size (T3: 43% and T4: 36.7%, p = 0.023) and samples with high FMNL1 expression were exclusively either T3 or T4 tumors (50%/50%)." (PMID 34115237, 2021). "Elevated expression of FMNL1 was associated with larger tumor size and with more advanced disease stage." (PMID 34115237, 2021). "In TCGA cohort, high FMNL1 expression was associated with tumor pathological grade, clinical stage and tumor metastasis." (PMID 33324547, 2020). "Here, we report that FMNL1 expression is associated with unfavorable prognosis in GBM and that FMNL1 regulates tumor migration and invasion via DIAPH1 and GOLGA2." (PMID 31861134, 2019). "The significant association of FMNL1 with lamellipod, focal adhesion, invadopod, metastasis, and migration-related gene sets further strengthens the idea that this gene affects the aggressive phenotype of the tumor." (PMID 40864802, 2025). "As a result, we hypothesized that varied prognostic characteristics in diverse malignancies were caused by the balance of FMNL1 expression in tumor and immune cells." (PMID 37859818, 2023). "Elevated FMNL1 was associated with larger tumor size and higher disease stage." (PMID 34115237, 2021). "FMNL1 expression was closely associated with tumor metastasis in our and TCGA cohort." (PMID 33324547, 2020). "Formins, which are potent regulators of actin dynamics, may be involved in tumor invasion and metastasis promotion; and emerging evidence has already implicated FMNL1, FMNL2, and FMNL3 in these processes." (PMID 31861134, 2019). "In the study of Kilpinen and his team in 2008, the FMNL1 mRNA expression profile was obtained in both healthy and tumor samples of 18 different tissue types, and its expression was observed, albeit slightly, in both healthy and tumor tissues of the prostate." (PMID 40864802, 2025). "Due to this specific expression pattern, FMNL1 mRNA expression in tumor tissues was largely sourced from TIICs from bulk RNA-seq analysis." (PMID 37859818, 2023). "As revealed in this research based on scRNA-seq and mQIF, FMNL1 is highly expressed in immune cells instead of tumor cells in HCC." (PMID 37859818, 2023). "According to the results of the ESTIMATE algorithm in HCC, tumors with high FMNL1 expression had lower tumor purity but higher TIIC infiltration." (PMID 37859818, 2023). "The difference of PD-L1 between high and low FMNL groups was detected because FMNL1 is a marker of tumor-infiltrating immune cells, and tumors with many immune cells are hot tumors." (PMID 36124068, 2022). "Here, we analyzed the expression of FHOD1 and FMNL1 in intestinal-type tumor samples of the stomach, gastrointestinal junction and distal esophagus and investigated their association with clinical data, including GC molecular subtypes." (PMID 34115237, 2021). "Similar to the results of TCGA_KIRC datasets, an increased FMNL1 mRNA level was observed in 10 tumor samples compared with paired adjacent normal tissues (p=0.0012)." (PMID 34659547, 2021). "High expression of FMNL1 correlated significantly with tumor stage and distant metastasis (P<0.05) both in the TCGA-KIRC datasets and expanded validation sets." (PMID 34659547, 2021). "High expression of FMNL1 is significantly correlated with advanced tumor stage, higher pathological tumor grade, tumor metastasis, and unfavorable prognosis in two independent cohorts containing over 800 patients with ccRCC." (PMID 33324547, 2020).
tumor (continued). "Collectively, our data suggest FMNL1 serve as a promising prognostic factor in ccRCC and function as an oncogene to promote tumor metastasis through upregulation of CXCR2." (PMID 33324547, 2020). "Collectively, our findings suggest FMNL1 works with HDAC1 to induce the expression of CXCR2 to promote tumor metastasis." (PMID 33324547, 2020). "The tail vein injection metastasis nude mouse model was used to test the FMNL1-mediated tumor metastasis." (PMID 33324547, 2020). "Functionally, FMNL1 was able to activate the epithelial to mesenchymal transition (EMT) to promote tumor progression." (PMID 33324547, 2020). "Ectopic expression of FMNL1 promotes, whereas FMNL1 depletion inhibits cell migration in vitro and tumor metastasis in vivo." (PMID 33324547, 2020). "Patients expressing more FMNL1 in tumor tissues survival much shorter and experienced tumor relapse in a much shorter time." (PMID 33324547, 2020). "In terms of mechanisms, in addition to mediating cytoskeletal remodeling, FMNL1 could promote tumor cell aggressiveness through multiple mechanisms." (PMID 37859818, 2023). "Behind the tight immunological correlation, whether FMNL1 plays a critical role in regulating TME or it is just a biomarker for tumor-infiltrating immune cell (TIIC) should be further investigated." (PMID 37859818, 2023). "FMNL1 could intensify the aggressiveness of tumor cells intensify the aggressiveness of tumor cells through a variety of ways, in addition to facilitating cytoskeletal remodeling." (PMID 36124068, 2022). "As a result, we hypothesized that FMNL1+ immune cells had a higher level of ability to migrate, making them more likely to play anti-tumor roles." (PMID 36124068, 2022). "An interesting research revealed that formin homology 2 domain containing 1 (FHOD1) and formin‐like 1 (FMNL1), family members of Formin, are correlated with tumor‐infiltrating lymphocytes in gastric cancer, which first linked Formin proteins with anti‐tumor immunity." (PMID 36311172, 2022). "Based on these observations, we subsequently regarded the endothelial staining and plasma cells as internal positive controls for FHOD1 stainings in the tumor samples, and lymphocytes and muscle cells were, respectively, regarded as internal positive controls for FMNL1." (PMID 34115237, 2021). "In contrast to a previous finding, such association was not seen with tumor cell FMNL1 expression and number of infiltrated lymphocytes." (PMID 34115237, 2021). "The over-expression of FMNL1 was significantly correlated with tumor stage and distant metastasis." (PMID 34659547, 2021). "In contrast, FMNL1 knockdown substantially inhibited the tumor formation in the lung." (PMID 33324547, 2020). "Furthermore, Human Tumor Metastasis RT2 ProfilerTM PCR Array consisting of 84 well-known metastasis-related genes was used identify the potential downstream effectors of FMNL1 in ccRCC cells." (PMID 33324547, 2020). "In vitro and in vivo data demonstrated that FMNL1 overexpression was able to promote cell migration and tumor metastasis, which was in line with previous studies showing that RNAi-mediated silencing of FMNL1 markedly weakened the cell migration potent in human cancer cells." (PMID 33324547, 2020). "The mechanism of FMNL1-mediated tumor metastasis was next investigated." (PMID 33324547, 2020). "Current literatures showed that FMNL1 incorporates with HDAC1 to facilitate tumor metastasis and that CXCR2 expression could be modulated by HDAC proteins." (PMID 33324547, 2020). "The axis of GATA3/FMNL1/CXCR2 may present a promising therapeutic target for tumor metastasis in ccRCC." (PMID 33324547, 2020). "In addition, FMNL1 was also could be detected in tumor cells, which acted as a critical oncogene in multiple cancers." (PMID 37859818, 2023). "Moreover, FMNL1 was highly expressed in tumor-infiltrating immune cells (TIICs) in tumor tissues." (PMID 36124068, 2022).
tumor (continued). "Furthermore, our results demonstrate a correlation between FMNL1 expression and tumor size as well as tumor stage, suggesting that FMNL1 may play a role in tumor progression in intestinal GC." (PMID 34115237, 2021). "Bulk FMNL1 mRNA expression was positively correlated with ESTIMATE Score, Immune Score, and Stromal Score but negatively correlated with Tumor Purity." (PMID 37859818, 2023). "To further explore the role of FMNL1 in formation of the inflamed tumor microenvironment (TME) in HCC patients, we firstly divided the immune subpopulations into FMNL1+ and FMNL1- based on the expressed count of FMNL1." (PMID 37859818, 2023). "The possible relationship between FMNL1 and FHOD1 with the tumor immune infiltrating lymphocytes in GC is still largely unstudied." (PMID 34115237, 2021). "Several key proteins such as MAP2K1, ITGB4, ITGA6, PTPN6, FMNL1, ANXA1, and MMP9 that modulate cell motility and tumor cell invasion were upregulated in MIBUC." (PMID 32326232, 2020). "High expression of FMNL1, with the help of HDAC1, upregulates CXCR2 to trigger EMT process and to facilitate cell migration and tumor metastasis in ccRCC." (PMID 33324547, 2020). "In addition, malignant cells also had frequent interactions with myeloid (FMNL1+) cells via many ligand-receptor pairs, such as OSMR-OSM, which took participate in the process and invasion of tumor cells 44-47." (PMID 37859818, 2023). "For example, T/NK (FMNL1+) cells communicated with malignant cells via CCR6-CCL20, which involved in the recruitment of T/NK cells 40, 41 and promoted the invasion and metastasis of tumor cells." (PMID 37859818, 2023). "Because FMNL1 is highly expressed in immune cells rather than tumor cells, the expression of FMNL1 mRNA in tumor tissues is derived primarily from TIICs using bulk RNA-seq analysis." (PMID 36124068, 2022). "The expression of FHOD1 and FMNL1 proteins was characterized in GC cells, and in non-neoplastic and malignant tissues utilizing tumor microarrays of intestinal GC representing different molecular subtypes." (PMID 34115237, 2021). "In summary, our study identified TOP2A, NCF4, FMNL1 and DOK3 as potential effective neoantigens for KIRC mRNA vaccine development, and patients with RIS2 tumor might benefit more from mRNA vaccination." (PMID 34872567, 2021). "qRT-PCR showed that FMNL1 mRNA level in ccRCC specimens was significantly higher than that in the nontumorous tissues adjacent to tumor." (PMID 33324547, 2020). "Strikingly, FMNL1 expression in patients with tumor metastasis was much higher than that in patients without tumor metastasis." (PMID 33324547, 2020). "Simultaneously, based on high positive rate of FMNL1 in CD45+ cells predicting prolonged OS verified in this research, we speculated that FMNL1+ immune cells had stronger migration capability, increasing their propensity to act as anti-tumor roles." (PMID 37859818, 2023). "Tumor cell FMNL1 expression did not correlate with lymphocyte infiltration." (PMID 34115237, 2021). "In addition, elevated FMNL1 expression correlated significantly with tumor stage (p = 0.004) regardless of the sample location (central or peripheral)." (PMID 34115237, 2021). "In this research, based on public data and biological validation, we found that FMNL1 was just a novel biomarker for immune cells in HCC, but was not an immunologically correlated gene in tumor cells." (PMID 37859818, 2023).
adenocarcinoma (1 paper, 2023). A common cancer characterized by the presence of malignant glandular cells. "Then, mQIF was employed to validate the expression pattern of FMNL1 using co-staining of FMNL1, CD45 (a biomarker for most immune cells), and CK8 (a biomarker for glandular epithelium and adenocarcinoma cell)." (PMID 37859818, 2023).
infection (1 paper, 2019). The state of being infected such as from the introduction of a foreign agent such as serum, vaccine, antigenic substance or organism. "We established stably expressing FLAG-tagged FMNL1 or FLAG-tagged EGFP from these cell lines by infection with corresponding lentiviral vectors." (PMID 31861134, 2019).
inflammation (1 paper, 2020). Aberrant reaction of the microcirculation characterized by movement of fluid and leukocytes from the blood into extravascular tissues. "Additionally, FMNL1 expression has been reported to be transcriptionally upregulated by T cells that migrate to sites of autoimmune inflammation." (PMID 32510333, 2020).
FMNL1 also shares sentences with these, for which no sentence is quoted: breast carcinoma (3 papers); colorectal cancer (3); non-small cell lung carcinoma (3); asthma (2); basophilic leukemia (1); fibrosis (1); focal segmental glomerulosclerosis (1); glioma (1); glomerular disease (1); hematological cancers (1); hematological malignancies (1); lymphoid leukemia (1); lymphoid tumors (1); Salmonella Infections (1); schizophrenia (1).